PLK1 (polo like kinase 1)
Diseases named in the same sentence as PLK1 in open-access papers (continued):
Sharing a sentence is not in itself a finding about the gene and the disease.
cervical carcinoma (continued). "The Expression Atlas database was searched for querying PLK1 expression in different cervical cancer cell lines and different tissues in the context of pan-cancer." (PMID 33354424, 2020). "PLK1 showed medium expression in all cervical cancer cell lines except TC-YIK cell line from Cancer Genome Project-cervical small cell carcinoma." (PMID 33354424, 2020). "Immunohistochemistry was performed for evaluating PLK1 expression between cervical cancer (including cervical squamous cell carcinoma (CESC) and cervical adenocarcinoma) and non-cancer samples." (PMID 33354424, 2020). "Great efforts will be committed to developing nanovectors directed against PLK1 for improved diagnose and treatment of cervical cancer." (PMID 33354424, 2020). "Kaplan-Meier survival curves showed that the event-free survival rate of cervical cancer patients with higher expression of PLK1 was shorter than that of patients with lower PLK1 (HR = 2.020, P = 0.0197)." (PMID 33354424, 2020). "Although several researches involved PLK1 in cervical cancer, PLK1 expression in cervical cancer was detected with single methods and small samples by those studies." (PMID 33354424, 2020). "We emphasized on the clinic-pathological significance of PLK1 in cervical cancer in this study, in vitro and in vivo experiment was required in future work for further validating the functional role of PLK1 on biological process of cervical cancer." (PMID 33354424, 2020). "Although the expression and clinic-pathological value of PLK1 in cervical cancer have been studied, the research methods in previous studies were single and the number of samples is limited." (PMID 33354424, 2020). "The overexpression of PLK1 in cervical cancer and the contributory effect of it on clinical progression indicated the hopeful prospect of PLK1 as a biomarker for cervical cancer." (PMID 33354424, 2020). "In conclusion, we have provided evidence that there is a correlation between overexpressed PLK-1 and the primary cancer stage in cervical carcinoma tissues." (PMID 19775446, 2009). "In the present study, we demonstrated, for the first time, that PLK-1 is expressed in cervical carcinoma with a positive rate of 88.9%, and PLK-1 expression in tumors was associated with primary tumor progression (T stage)." (PMID 19775446, 2009). "To further understand the importance of PLK-1 in the management of cervical carcinoma, we used siRNA transfection to knock down PLK-1 production in HeLa cells." (PMID 19775446, 2009). "Based on these results, PLK-1 knockdown shows promise as an adjuvant chemotherapy for cervical carcinoma." (PMID 19775446, 2009). "To address this issue, we investigated the expression and distribution of PLK-1 in cervical carcinoma tissues." (PMID 19775446, 2009). "To investigate the presence of aberrant PLK-1 expression in human cervical carcinoma tissues, we examined PLK-1 expression by immunohistochemical staining." (PMID 19775446, 2009). "Moreover, multiple analyses of cancerous and healthy tissue samples derived from individuals with cervical cancer showed that PLK1 was overexpressed in cervical cancer tissues." (PMID 34093198, 2021). "Therefore, PLK1 presents an ideal target for the development of specific small molecule inhibitors for cervical cancer treatment." (PMID 34093198, 2021). "Existing studies of PLK1 in cervical cancer had several flaws." (PMID 33354424, 2020). "The effect of PLK1 expression on the overall survival, disease-free survival and event-free survival of cervical cancer patients was analyzed through Kaplan Meier survival curves for cervical cancer patients from RNA-seq and GSE44001 datasets." (PMID 33354424, 2020). "We conjectured that the overexpression of PLK1 in cervical cancer and the oncogenic influence of it on clinical progression of cervical cancer may result from the loss of miR-100 expression and negative transcriptional regulation." (PMID 33354424, 2020).
cervical carcinoma (continued). "Here, we provided sufficient evidence of PLK1 overexpression in cervical cancer." (PMID 33354424, 2020). "The adverse influence of PLK1 expression on cervical cancer patients might be attributed to the promotive effect of PLK1 on the clinical progression of cervical cancer." (PMID 33354424, 2020). "Both mutation and genetic alteration profiles of PLK1 suggested that missense mutation occurred in PLK1 gene, which might explain the overexpression of PLK1 in cervical cancer." (PMID 33354424, 2020). "In this study, a total of 963 cervical cancer samples and 178 non-cancer samples collected from in-house tissue microarrays and exterior microarrays and RNA-seq datasets were used for comprehensive assessment of the clinic-pathological significance of PLK1 in cervical cancer." (PMID 33354424, 2020). "Furthermore, nanoparticles targeting PLK1 in serum of cervical cancer tissues possess unlimited potential of clinical diagnose and treatment for cervical cancer." (PMID 33354424, 2020). "We also noted that PLK1 expression exerted contradictory influence on survival of cervical cancer patients from GSE44001 and TCGA database, which might be explained by the difference of source of cervical cancer patients." (PMID 33354424, 2020). "PLK1-related carcinogenesis of cervical cancer might relate to the active involvement of correlated genes in pathways such as DNA replication, cell cycle, mismatch repair and homologous recombination." (PMID 33354424, 2020). "The upstream regulation of miRNA might provide possible explanation for the molecular mechanism of PLK1 in cervical cancer." (PMID 33354424, 2020). "The clinic-pathological significance of PLK1 in cervical cancer." (PMID 33354424, 2020). "Previous studies demonstrate that PLK1-mediate the activation of phosphorylates glucose-6-phosphate dehydrogenase which is critical for the promoting the cell cycle progression and tumor growth in liver cancer and cervical cancer." (PMID 31488217, 2019). "In light of the hypothesized tumor suppressive role of PLK3 in cervical cancer, we advise caution in future clinical investigations regarding the utility of PLK1 inhibitors in this setting." (PMID 31475104, 2019). "We examined PLK-1 expression in cervical carcinoma tissues using immunohistochemical staining." (PMID 19775446, 2009). "To further characterize the role of PLK-1 in the carcinogenesis of cervical carcinoma and the importance of PLK-1 knockdown in the prevention of cervical carcinoma, we investigated the effects of PLK-1 RNA interference on cell cycle characteristics and apoptosis in HeLa cells." (PMID 19775446, 2009). "However, little is known about the importance of PLK-1 in the development and management of cervical carcinoma." (PMID 19775446, 2009). "At present, the treatment of recurrent cervical cancer remains largely ineffective, and efforts in cancer drug development are currently focused on critical serine/threonine kinases, such as death-associated protein kinase 1 (DAPK1) and polo-like kinase 1 (PLK1)." (PMID 35154442, 2022). "Thus, it is speculated that PLK1 may also promote lymph node metastasis of cervical cancer by interacting with genes such as STAT3 or regulating certain pathways in cervical cancer." (PMID 33354424, 2020). "Therefore, targeting PLK-1 might be a promising strategy for enhancing sensitivity to chemotherapeutic reagents in cervical carcinoma." (PMID 19775446, 2009). "Therefore, PLK-1 can be thought of as a potential target for preventing cervical carcinoma." (PMID 19775446, 2009). "Therefore, our results indicate that PLK-1 may be a potential target for tumor evaluation and management of cervical carcinoma." (PMID 19775446, 2009). "In cervical cancer cells, DAPK1 is autophosphorylated at Ser308 during the G2 phase and mitosis, and this phosphorylation is further regulated by Polo-like Kinase 1 (PLK1), a key mitotic regulator, particularly during the G2/M phase." (PMID 40918124, 2025).
cervical carcinoma (continued). "Expression pattern and discriminatory capacity of PLK1 in CESC, cervical adenocarcinoma and all types of cervical cancer was visualized in a panel of violin plots and ROC curves." (PMID 33354424, 2020). "It is worth noting that the high expression of PLK1 is significantly correlated with lymph node metastasis of CESC and all types of cervical cancer patients." (PMID 33354424, 2020). "According to the literature, investigating the importance of PLK-1 in the prevention of other cancers, we believe PLK-1 can be considered an important candidate for the enhancement of chemosensitivity in cervical carcinoma." (PMID 19775446, 2009). "With respect to the prognostic value of PLK1 in cervical cancer, we are the first group to appraise the expression of PLK1 on overall survival, disease-free survival, and event-free survival of CESC, cervical adenocarcinoma and all types of cervical cancer patients." (PMID 33354424, 2020). "Among them, PLK1, ATM, CDK5 and CHEK1 are abnormally expressed in cervical cancer." (PMID 32655987, 2020). "The evaluation of clinic-pathological significance of PLK1 in cervical cancer by previous studies is incomplete, lacking assessment of prognostic value." (PMID 33354424, 2020). "According to the expression data of PLK1 in 290 cervical cancer tissues and 13 non-cancer tissues, PLK1 presented significantly higher protein expression in cervical cancer tissues than in non-cancer tissues (X2 = 11.108, P = 0.001)." (PMID 33354424, 2020). "Also, it was found that PLK1 expression was negatively correlated with miR-100 expression in CIN3 and cervical cancer tissues." (PMID 24840898, 2014). "Consequently, it is conceivable that dysregulation of NCAPG2 and PLK1 localization and regulation, possibly mediated by HPV-16 E7, may contribute to the pathogenesis and progression of cervical cancer." (PMID 37248471, 2023). "Indeed, knockdown or inhibition of PLK1, CDK1, AURKA, MELK, and NEK2 resulted in reduction or repression of metastatic potential and invasiveness of various cancer types, including mCRPC and cervical cancer." (PMID 34680307, 2021). "Moderate and even strong immunostaining of PLK1 could be observed in 61.7% of cervical cancer samples while 84.6% of non-cancer cervix samples presented negative or weak immunostaining of PLK1." (PMID 33354424, 2020). "Overexpression of PLK1 could well distinguish cervical cancer from non-cancer tissues (AUC = 0.842, P < 0.001)." (PMID 33354424, 2020). "A total of 17 cervical cancer cell lines including C-33 A, C-33-A, C-4-1, Ca Ski, Ca-Ski, DoTc2-4510, HeLa, HEp-2, HT-3, ME-180, MS751, OMC-1, SiHa, SISO, SKG-IIIa, SW756 and TC-YIK from the Cancer Genome project and 675 Genentech project were retrieved for PLK1 expression." (PMID 33354424, 2020). "However, the significance of PLK-1 in the pathogenesis and management of cervical carcinoma is not well-understood." (PMID 19775446, 2009).
esophageal cancer (30 papers, 2010 to 2026). A primary or metastatic malignant neoplasm involving the esophagus. "While previous literature indicated that PLK1 modulates STAT3 transcription via β-catenin in esophageal cancer cell lines, our results showed that siRNA-mediated PLK1 knockdown only moderately reduced STAT3 transcription." (PMID 41539998, 2026). "Constitutively activated STAT3 and positively regulated PLK1 collectively enhanced proliferation and apoptosis resistance in the esophageal cancer cell line KYSE510." (PMID 38273295, 2024). "Studies have shown that PLK1 is closely related to cell mitosis, but recent studies have also found that PLK1 protects esophageal cancer cells from anoikis through regulating β-Catenin protein levels by inhibiting their degradation." (PMID 37081871, 2023). "We previously reported that moscatilin can induce apoptosis and mitotic catastrophe in esophageal cancer cells, accompanied by upregulation of polo-like kinase 1 (Plk1) expression." (PMID 30764514, 2019). "In preliminary work, we found that moscatilin suppressed the growth of esophageal cancer cells by inducing apoptosis and mitotic catastrophe concomitantly with increased expression of polo-like kinase 1 (Plk1)." (PMID 30764514, 2019). "The study also demonstrated that RNA interference mediated PLK1 RNA inactivation led to a decrease in STAT3 transcriptional activity in esophageal cancer cells." (PMID 29983892, 2018). "PLK1 was found overexpressed in esophageal cancer and showed promising prognostic efficacy." (PMID 38273295, 2024). "PLK1 protects esophageal carcinoma cells from anoikis through regulating β‐catenin protein levels." (PMID 36507553, 2023). "Downregulation of PLK1 can inhibit the invasion and metastasis of esophageal cancer cells." (PMID 34917126, 2021). "In the present study, we investigated whether moscatilin would suppress esophageal cancer cell growth and increase Plk1 expression in vivo." (PMID 30764514, 2019). "For the PLK1 kinase, it had been demonstrated that overexpressed PLK1 in esophageal cancer could be targeted by miRNA-593." (PMID 26090465, 2015). "However, there was report that demonstrated PLK1 expression could be target by miRNA to regulate the cell proliferation in esophageal cancer, which implied that PLK1 could be used as the therapeutic target." (PMID 26090465, 2015). "One study in esophageal cancer revealed that STAT3 and PLK1 control each other’s transcription in a positive feedback loop." (PMID 29983892, 2018). "Additionally, GSEA enrichments revealed the suppression of cell cycle and mitotic checkpoint regulatory (AURKB, PLK1, and E2F) and the DDR and DNA-repair (ATR, BARD1, and FANCONI) pathways by STL001 in esophageal cancer." (PMID 38697979, 2024). "Similarly, STAT3 was shown to form a reciprocal regulatory loop with Polo-like kinase 1 (PLK1) to enhance the proliferation and survival of esophageal cancer cells." (PMID 24995504, 2014).
osteosarcoma (30 papers, 2010 to 2025). A usually aggressive malignant bone-forming mesenchymal neoplasm, predominantly affecting adolescents and young adults. "Plk1 inhibition has been shown to cause cell death in osteosarcoma cells and its expression correlates with overall survival in osteosarcoma patients." (PMID 26807203, 2015). "Furthermore, we also confirmed that PLK1 dysregulation is closely associated with osteosarcoma tumorigenesis, particularly with poor prognosis, in line with the results from previous independent studies." (PMID 37419907, 2023). "Silencing the PLK1 gene in combination with chemotherapy significantly inhibits tumors, promotes osteosarcoma cell apoptosis, and establishes a novel low-toxicity tactic for osteosarcoma clinical treatment." (PMID 40868764, 2025). "In the present study, we first explored the effects of hfCas13d‐mediated PLK1 knockdown on osteosarcoma cell viability, apoptosis, proliferation and invasion to elucidate the role of PLK1 in osteosarcoma cells." (PMID 38780513, 2024). "Taken together, these data suggest PLK1 silencing attenuates the invasive phenotype of osteosarcoma cells, likely by restoring epithelial characteristics." (PMID 38780513, 2024). "In summary, the results demonstrate that targeted PLK1 suppression mediated by hfCas13d substantially reduces osteosarcoma cellular viability and proliferative capacity." (PMID 38780513, 2024). "Taken together, this study highlights PLK1 as a potential therapeutic target and driver of disease progression in osteosarcoma." (PMID 38780513, 2024). "Our findings highlight PLK1 as a potential therapeutic target in osteosarcoma and demonstrate the utility of CRISPR‐Cas13d technology for targeted gene suppression." (PMID 38780513, 2024). "Overexpression of polo‐like kinase 1 (PLK1) is frequent in osteosarcoma and drives disease progression and metastasis, making it a promising therapeutic target." (PMID 38780513, 2024). "PLK1 was found to be significantly upregulated in osteosarcoma tumour tissues compared to normal bone." (PMID 38780513, 2024). "In this study, we demonstrated that PLK1 is upregulated in osteosarcoma tissues and its overexpression correlates with poorer clinical outcomes." (PMID 38780513, 2024). "Next, we aimed to apply the hfCas13d system to knock down the expression of PLK1 in PDAC osteosarcoma cells." (PMID 38780513, 2024). "Lentiviral vectors encoding hfCas13d and PLK1‐targeting sgRNAs were transduced into MG‐63 and U2OS osteosarcoma cells." (PMID 38780513, 2024). "sgRNA‐mediated PLK1 suppression via hfCas13d transfection inhibited osteosarcoma cell proliferation, induced G2/M cell cycle arrest, promoted apoptosis, reduced cell invasion and increased expression of the epithelial marker E‐cadherin." (PMID 38780513, 2024). "To investigate the clinical relevance of PLK1 in osteosarcoma, we analysed PLK1 expression using the GEPIA database." (PMID 38780513, 2024). "Overall, this study establishes a foundation for additional investigation into targeted PLK1 inhibition hfCas13d‐mediated gene knockdown as a novel therapeutic approach in osteosarcoma." (PMID 38780513, 2024). "Using the CRISPR‐hfCas13d system, we achieved robust and specific knockdown of PLK1 in two osteosarcoma cell lines, MG‐63 and U2OS." (PMID 38780513, 2024). "In this study, we explored PLK1 knockdown in osteosarcoma cells using RNA interference mediated by high‐fidelity Cas13d (hfCas13d)." (PMID 38780513, 2024). "Our findings highlight the oncogenic functions of PLK1 in promoting osteosarcoma progression and suggest PLK1 is a promising therapeutic target in this disease." (PMID 38780513, 2024). "Conversely, PLK1 exhibited an increase in protein expression similarly to osteosarcoma cell line models." (PMID 38791684, 2024). "We next evaluated the effects of PLK1 knockdown on osteosarcoma cell viability and colony formation ability." (PMID 38780513, 2024).